RN7SL3 (RNA component of signal recognition particle 7SL3)
Synonyms: 7L30.2; RNSRP3; RN7SL631P
Gene: Miscellaneous RNA gene on chromosome 14 (49,853,616 to 49,853,914, reverse strand). Ensembl gene ENSG00000278771.
Gene Ontology:
Biological process: SRP-dependent cotranslational protein targeting to membrane, signal sequence recognition
Cellular component: signal recognition particle, endoplasmic reticulum targeting
Homologues: Orthologues: chimpanzee Metazoa_SRP (99% identical), macaque Metazoa_SRP (99% identical), rat Metazoa_SRP (87% identical). Paralogues in human: RN7SL1 (98% identical), RN7SL2 (96% identical), RN7SL230P (88% identical), RN7SL126P (88% identical), RN7SL5P (88% identical), RN7SL220P (87% identical), RN7SL296P (87% identical), RN7SL493P (87% identical), RN7SL278P (86% identical), RN7SL45P (86% identical), RN7SL664P (86% identical), RN7SL769P (86% identical), and 704 more.